PGR (progesterone receptor)
Diseases named in the same sentence as PGR in open-access papers (continued):
Sharing a sentence is not in itself a finding about the gene and the disease.
cancer (continued). "In contrast, the greatest anti-cancer activities were seen with the E2 and P4 combination protocols that could provide a superlative alternative therapeutic strategy against CRC, possibly by ERβ and PGR-mediated androgen deprivation and inhibition of ERα-induced cancer progression." (PMID 36263327, 2022). "Our study showed varying levels of estrogen and progesterone receptor expression in primary and paired recurrent tumors, supporting the use of early endocrine maintenance therapy in the first-line setting, following standard chemotherapy for estrogen and/or progesterone receptor positive cancer." (PMID 36430718, 2022). "Proteins including progesterone receptor (PR), epidermal growth factor receptor (EGFR), mechanistic target of rapamycin (mTOR), p53R2, cytotoxic T-lymphocyte–associated antigen 4 (CTLA-4), cyclin dependent kinase-(CDK8), etc. can be used as therapeutic targets to stop cancer from progressing." (PMID 36235128, 2022). "Hence, in the present study, we investigated the potential of ESR1, ESR2, and PGR as predictive and prognostic biomarkers in multiple cancer types from an immuno-oncological perspective based on bioinformatics analysis to provide a reference for future studies and the application of immunotherapies." (PMID 34322374, 2021). "Interestingly, our panel included genes already described to be cancer predisposition genes (FAS, ITK, KIF1B, PGR and MET) or previously reported as playing important roles in cancer (ABI1, ARID5B, DNMT3A, HEY1, KDM5C, NCOA1, NUP98, and SLC34A2), or in DNA repair process (FANCF)." (PMID 30925779, 2019). "This type of cancer shows a major tendency toward early metastasis, and does not respond to hormonal chemotherapy, as it lacks the three main molecular targets, the estrogen receptor (ER), the progesterone receptor (PR), and the human epidermal growth factor receptor (HER-2/Neu)." (PMID 27775632, 2016). "In addition to changes in their shape and size, IR imaging and statistical analyses revealed that three different cancer cell lines which have different characteristic in terms of cancer classification (ER, PgR, ERBB2 amplification) induce similar modifications of the fibroblasts IR spectra." (PMID 25390361, 2014). "According to menopausal status, starting to smoke at an early age of ≤19 years was significantly associated with an increased risk of postmenopausal ER-/PgR- cancer, although there was no linear relationship between age at the start of smoking and the risk of ER-/PgR- cancer." (PMID 24516791, 2014). "Through integrative analysis using univariate regression, LASSO-Cox regression, and multivariate Cox regression, PGR and RPS6KA1 were identified as core targets involved in curcumol’s anti-cancer effects in EC." (PMID 40678730, 2025). "GSEA enrichment analysis revealed that PGR and RPS6KA1 were upregulated in metabolic pathways related to matter and energy, while downregulated in developmental and cancer-related pathways." (PMID 40678730, 2025). "The tendency of ER, PgR, HER2, and Ki67 status on BMI differed by menopause status; premenopausal cases with a lower BMI showed higher proportions of ER- and PgR-positive cancer and lower proportions of cancer with high Ki67." (PMID 40259174, 2025). "Based on the drug information, 29 sex-biased mRNAs were drug-targeted genes and six (CD38, PGR, ESR1, GABRP, F3, PRKCB) of them were targeted by cancer therapeutic drugs." (PMID 39175079, 2024). "Recent studies have demonstrated that the administration of aglepristone, a progesterone receptor antagonist, inhibits the proliferation index in PGR-positive canine carcinomas and increases the disease-free period." (PMID 38256245, 2024). "With this approach, the canonical cancer cells SK‐BR‐3, MCF‐7, and MDA‐MB‐231, maintain their characteristic expression of markers (i.e., ERα, HER2, and PGR) while developing distinct morphology." (PMID 37693069, 2023).
cancer (continued). "The macrophage infiltration was compared to GATA-3, estrogen receptor (ER), progesterone receptor (PR), human epidermal growth factor receptor 2 (HER-2), and Ki-67 expression in cancer cells." (PMID 36996051, 2023). "Antagonism, for most of the selected targets (genes in purple), and agonism, for PGR, PPARA, and VDR (genes in red), were proposed as potential approaches for anti‐aging and anti‐cancer treatment." (PMID 37888486, 2023). "Although the altered expression of YTHDC1 has been linked with m6A modification machinery and the effect on oncogenic factors, such as BRCA2 or PGR, it has yet to be addressed how YTHDC1 affects splicing or export in cancer cells." (PMID 35563766, 2022). "Therefore, we suggest that dual activation of ERβ and PGR by their ligands could initiate a cascade of cellular anti-cancer events involving inhibition of cancer progression induced via AR and ERα pathways alongside promoting anti-proliferative and pro-apoptotic activities." (PMID 36263327, 2022). "Each compound was docked with each cancer target protein, namely EGFR, NF-kB and progesterone receptor." (PMID 36144225, 2022). "The cancer genes are composed of genes that code for HER2 (HER2 and GRB7), oestrogen genes (ER, PGR, BCL2, and SCUBE2), proliferation genes (MKI67, STK15, BIRC5, CCNB1, and MYBL2), and invasion genes (MMP11 and CTSL2) as well as GSTM1, CD68, and BAG1." (PMID 36042999, 2022). "Gene expression and protein abundance for EpCAM/EpCAM, ESR1/ER, PGR/PGR, GATA3/GATA3 were detected in cancer epithelial cells." (PMID 36307545, 2022). "As a type of aggressive cancer, triple-negative breast cancer (TNBC) includes the estrogen receptor (ER), progesterone receptor (PR), and human epidermal growth factor receptor-2 protein (HER-2)." (PMID 35432487, 2022). "Through this comprehensive pan-cancer analysis, the feasibility of using ESR1, ESR2, and PGR as prognostic markers and therapeutic targets for multiple cancers was evaluated." (PMID 34322374, 2021). "Our study provides comprehensive evidence that ESR1, ESR2, and PGR are feasible prognostic markers and therapeutic targets for multiple cancers and that they could be a factor for disease prediction, disease evaluation, and individualized treatment in various types of cancer." (PMID 34322374, 2021). "With the demonstration of classical nuclear progesterone receptor (nPRs) in some cancers, e.g., breast, ovarian, and endometrial cancers, the hope was that the nPR was essential for cancer growth, so that by blocking the nPR cancer, progression could be halted." (PMID 34830233, 2021). "A 58-year-old woman with a locally advanced estrogen receptor positive (ER +), progesterone receptor positive (PR +), HER2-positive cancer received her first cycle of pertuzumab, trastuzumab, carboplatin, and docetaxel (PTCH) without incidence." (PMID 31641845, 2020). "We found that both HIF‐1α and HIF‐2α (EPAS1) have the ability to activate oncogenes deeply involved in cancer biology, such as VEGF, CXCL8 and PGR." (PMID 32537867, 2020). "The subgroups include proliferation genes (Ki67, STK15; Survivin, CCNB1, MYBL2), invasion genes (MMPP11, CTSL2), HER2 genes (GRB2, HER2), estrogen genes (ER, PGR, BCL2, SCUBE2), and other cancer related genes (GSTM1, CD68, BAG1)." (PMID 33665165, 2020). "Hence, neither the presence of oestrogen receptor nor progesterone receptor exposure to the cancer cells surface may be the initial target for recombinant javanicin to bind to, which would in turn cause cancer cell death." (PMID 31804594, 2019). "The expression of ER, progesterone receptor (PR) and the human epidermal growth factor receptor 2 (HER2) represents the groundwork for the classification of this type of cancer and is useful for prognostic prediction and therapy selection." (PMID 31877692, 2019). "Information about the biomarkers estrogen receptor (ER), progesterone receptor (PR), HER2 and Ki-67 was known for 157 out of 166 invasive cancers." (PMID 30092817, 2018).
cancer (continued). "A PgR staining rate of 50% was the most significant cutoff for predicting recurrence-free survival (RFS) and cancer-specific survival (CSS)." (PMID 30080878, 2018). "Out of 44 evaluable tumors (2 patients had bilateral carcinoma), 54.5% were HER2-positive (ER+/Progesterone Receptor (PgR)+, 16%; ER+/PgR-, 13.5%; ER-/PgR-, 25%) and 45.5% HER2-negative (ER+/PgR+, 18.5%; ER+/PgR-, 13.5%; ER-/PgR-, 13.5%)." (PMID 29937992, 2018). "Recurrence-free survival (RFS) and cancer-specific survival (CSS) were analyzed according to Ki67 LI and PgR expression, and significant cut-off values for selecting patients with a poor prognosis were evaluated." (PMID 28532429, 2017). "Mitotic activity of ER + PgR- tumors seems unrelated to the HER2 status, possibly as an indicator that ER dysfunctionality in cancers that lack PgR expression." (PMID 28356061, 2017). "In this trial, researchers used an NGS platform similar to the one used in our study (AmpliSeq for cancer panel), but used Cytoscan for CNV analysis and an IHC panel including estrogen receptor (ER), progesterone receptor (PR), and androgen receptor (AR)." (PMID 26396172, 2015). "In clinically, estrogen receptor (ER), progesterone receptor (PR), and human epidermal growth factor type 2 receptor (HER2) are established biomarkers for breast cancer diagnosis, cancer subtypes analysis and specific treatment guidance." (PMID 24225229, 2013). "Moreover, A20 overexpression has been associated with poor prognosis in ER and progesterone receptor (PR)-negative breast tumor cells; thus, it may be thought of as a new cancer biomarker." (PMID 23134590, 2012). "In the investigation of locoregional recurrence (LRR), the discordance rates between primary cancer and LRR was 9% for ER, 22% for PgR and 4% for HER2." (PMID 22004841, 2011). "Patients with ER and PgR negative primary tumors had increased HRs compared to patients with ER and/or PgR positive cancers (HR 1.41; CI 1.07–1.85 and HR 1.47; CI 1.14–1.89)." (PMID 41511682, 2026). "Despite these findings, the line was negative for the hormone receptors ER and PgR, even though the patient’s original cancer tissue contained a mixture of cells both positive and negative for both hormone receptors." (PMID 39878900, 2025). "Histology revealed No Special Type Invasive Carcinoma, Grade 3, Estrogen Receptor negative, Progesterone Receptor negative, Ki67 35% HER2 score 0; ypT2 (3.5 cm) N0 (0/9)." (PMID 39980563, 2025). "It has been shown that ESR1 and PGR were highly expressed in MCF7, T47D, and MDA-MB-361 metastatic cell lines, suggesting that these cancer cells represent models of estrogen- and progesterone-dependent cancers." (PMID 38339272, 2024). "TR may be defined as cancers with a similar molecular receptor profile (ER; oestrogen receptor / PR; progesterone receptor / HER2) and histological subtype (Ductal/Lobular/ductal carcinoma in situ) when compared to the originally treated cancer." (PMID 38433867, 2024). "Triple-negative breast cancer (TNBC) is characterized by the absence of three key receptors in cancer cells—estrogen receptor (ER), progesterone receptor (PR), and human epidermal growth factor receptor 2 (HER2)—making TNBC more difficult to treat." (PMID 39683831, 2024). "According to the literature, simple carcinomas show a higher expression of PGR in comparison with complex carcinomas, the lack of differentiation between simple and complex carcinomas in our study would dilute these possible differences." (PMID 38256245, 2024). "Most ALN + cancers were Bloom & Richardson grade I or II, estrogen and progesterone receptor positive and Her2/Neu negative." (PMID 37890215, 2023).
cancer (continued). "MGA, atypical MGA (AMGA), and the vast majority of MGA-associated carcinomas (MGACA) are negative for estrogen receptor (ER), progesterone receptor (PR), and human epidermal growth factor 2 (HER2) by immunohistochemistry." (PMID 37159793, 2023). "Twenty of the cancers (33%) were estrogen- and progesterone receptor–negative, so biologically significant, and not over diagnosed." (PMID 35621681, 2022). "Despite the tremendous efforts made in developing cancer biomarkers and liquid biopsy for past decades, only a few (less than 25) cancer biomarkers have been approved by FDA for clinical practice, such as Estrogen receptor (ER), Progesterone receptor (PR), HER-2/neu, CA-125, and PSA3." (PMID 35787656, 2022). "Triple-negative breast cancers (TNBC), forming the majority of the PAM50 criteria-classified basal-like cancer subtype, are defined by a lack of estrogen receptor (ER), progesterone receptor (PR) and human epidermal growth factor receptor 2 (HER2) expression." (PMID 35884422, 2022). "TNBC is a type of malignant tumor defined by the lack of estrogen receptor, progesterone receptor, and human epidermal growth factor receptor 2 expression." (PMID 33676555, 2021). "Additionally, prognostic analysis suggested that ESR1, ESR2, and PGR were significantly correlated with OS and RFS in patients with specific cancer types." (PMID 34322374, 2021). "In this study, we only reviewed results of cancers with ER and PgR expression from permanent pathology reports, without re-testing for HR." (PMID 34638491, 2021). "Triple-negative breast cancer (TNBC) is an aggressive metastatic breast cancer (MBC) cancer characterized by the absence of estrogen receptor (ER), progesterone receptor (PR), and human epidermal growth factor receptor 2 (HER2)." (PMID 33513992, 2021). "Pgrmc1 is a non-canonical progesterone receptor related to the lethality of various types of cancer." (PMID 34069911, 2021). "Beside its classical function such as steroid hormone synthesis and metabolic function as a non-genomic progesterone receptor, the relevance between Pgrmc1 and cancers has been suggested in diverse organs." (PMID 34069911, 2021). "Triple-negative breast cancer (TNBC) is an aggressive breast type of cancer with no expression of estrogen receptor (ER), progesterone receptor (PR), and human epidermal growth factor receptor-2 (HER2)." (PMID 33445543, 2021). "Interestingly, NR3C2, PGR, RORA were differentially expressed in all 16 cancer types, while HNF4G was differentially expressed in only 5/16 cancers (31.3%)." (PMID 32024906, 2020). "In 15% of cases, PgR expression is lost in ER(+) cancers, whereas a lack of nuclear ER expression in PgR(+) tumors is unusual." (PMID 32825530, 2020). "MF has been shown to inhibit in vitro the growth of cancer cells of reproductive and non-reproductive origin, independently of their PGR expression status." (PMID 33158280, 2020). "Stratification analysis yielded a similar association of rs13293512 CC genotype in patients with negative estrogen receptor or patients with negative progesterone receptor, or patients with T1-2 stage cancer, or patients with advanced cancer." (PMID 31028134, 2019). "Finally, we discovered eight genes (MME, SOX17, AGTR1, PGR, ESR1, PAX8, C3 and IRF6) with high amplification frequency compared to other genes across the cancer types." (PMID 31879572, 2019). "Breast cancer is a genetically heterogeneous group of tumors and can be further subdivided into several types, including luminal estrogen receptor- and progesterone receptor-positive (ER+/PR+), human epidermal growth factor receptor 2 (HER2)-positive, and triple-negative (ER−/PR−/HER2−) cancers." (PMID 31717460, 2019). "TNBC is a heterogeneous set of cancers grouped by their absence of estrogen receptor (ER), progesterone receptor (PR), and human epidermal growth factor receptor 2 (HER2/neu)." (PMID 31244777, 2019).
cancer (continued). "This family of cancer is negative for the expression of estrogen receptor (ER), progesterone receptor (PR), and human epidermal growth factor receptor 2 (HER2)." (PMID 31323788, 2019). "Ultrasound guided biopsy showed a high-grade carcinoma consistent with primary breast origin, oestrogen receptor (ER) and progesterone receptor (PR) negative, and HER-2 negative by fluorescent in situ hybridisation (FISH)." (PMID 31363168, 2019). "We measured not only the activation of p38 and downregulation of ERα, consistent with previous reports, but also found varied effects on the expression of anti-apoptotic Bcl-2 family proteins depending on the cell types as well as the downregulation of PgR and HER2 in multiple cancer cell lines." (PMID 30347895, 2018). "In the HER2‐negative cohort, 46% of the cancers were ER‐positive/progesterone receptor (PgR)‐positive, 7% were ER‐positive/PgR‐negative, 5% were ER‐negative/PgR‐positive, and 42% were ER‐negative/PgR‐negative." (PMID 29582557, 2018). "IgG-TAA score was significantly higher in HER2-positive tumors as compared to HER2- negative cancers [mean fold change (FC) = 1.81; P = 0.032] and showed a tendency to be increased in estrogen receptor (ER) and progesterone receptor (PR) negative cancers." (PMID 30515157, 2018). "The overall KIBRA-low expression was significantly associated with negative ER expression (p = 0.005), negative PgR expression (p = 0.001) and Ki67 positivity in < 14% of cancer cells (p < 0.001)." (PMID 29793439, 2018). "Seventeen percent of BRCA and UCEC express PGR and 9.4% of BRCA express ERBB2 in our cohort, reflecting the FDA-approved use of anti-estrogen hormone therapy and HER-2 inhibitors, respectively, in these cancer types." (PMID 30053901, 2018). "In the HER2‐positive cohort, 30% of the cancers were ER‐positive/PgR‐positive, 8% were ER‐positive/PgR‐negative, 3% were ER‐negative/PgR‐positive, and 59% were ER‐negative/PgR‐negative." (PMID 29582557, 2018). "Since the presence of hormone receptors, such as the estrogen receptor (ER), progesterone receptor (PR) and human epidermal receptor 2 (HER2) are critical for cancer cell growth, these receptors are often used for diagnosis and as therapeutic targets to treatment of breast cancer." (PMID 29719633, 2018). "Luminal B tumors, which account for approximately 20% of all BC, show a lower expression of estrogen receptor (ER), lower or no expression of progesterone receptor (PgR), and higher proliferation compared to luminal A cancers and can be HER2 positive." (PMID 29849822, 2018). "Triple-negative breast cancer (TNBC) represents a diverse group of cancers that are characterized by lack of expression of the estrogen receptor (ER), progesterone receptor (PR) and absence of HER2 amplification." (PMID 28817737, 2017). "One hundred and seventy-eight patients had “Luminal B” tumors expressing both (50.4%) or one hormonal receptor/s (20.8%), whereas 72 (28.8%) showed “HER2-enriched” tumors i.e., both ER/PgR negative cancers." (PMID 28915642, 2017). "In this study, estrogen and progesterone receptor positive (ER + /PR + ) IBH-6 and T47D cancer cells were stably modified to upregulate or downregulate specifically AKT1 or AKT2 isoforms and search for their specific effects on cell proliferation, adhesion and invasion." (PMID 28287129, 2017). "Triple‐negative breast cancer (TNBC) represents a heterogeneous group of cancers characterized by a lack of ER, PgR, and HER2 expression." (PMID 26775583, 2016). "The cancer cells were positive for ER, partially positive for progesterone receptor (PgR), and negative for HER2 expression (1+)." (PMID 27957354, 2016). "With immunohistochemistry (IHC), which does not require fresh material, ER and PgR are assessed in cancer cells only." (PMID 27722840, 2016).